TNF (tumor necrosis factor)
Diseases named in the same sentence as TNF in open-access papers (continued):
Sharing a sentence is not in itself a finding about the gene and the disease.
tumor (continued). "The N1 phenotype is involved in cytotoxic activity against tumor cells and its immune profile is characterized by high levels of TNFα, CCL3, ICAM-1 and low levels of Arginase." (PMID 32731512, 2020). "These analyses indicated that TNF/Mel/SM significantly increased tumour death compared to TNF/Mel alone (P = 0.0034, unpaired t‐test), in keeping with augmented therapy in this therapeutic cohort." (PMID 32419365, 2020). "Of note, tumor-homing CD4+ TRM are more potent producers of TNF and IFN-γ compared with other tumor infiltrating T cells." (PMID 32106536, 2020). "In the case of most cancer cells, TRAF2 is abundant, and the final outcome produced by TNFα is tumor growth." (PMID 32391269, 2020). "The fact that TNF mediates AICD in human tumor-reactive CD8 T cells suggests that the use of TNF-blocking agents can be exploited in immunotherapy strategies." (PMID 32292509, 2020). "TNFα is one of the major pro-inflammatory cytokines presented in COVID-19 patients, which has paradoxical effects on tumor growth." (PMID 33352869, 2020). "Subsequently, Vredevoogd and colleagues combined these earlier observations to show that increasing sensitivity of tumor cells to TNF killing by removal of TRAF2 enhanced the therapeutic effect of ICI drugs." (PMID 32053868, 2020). "TNF-α present in the tumor environment can induce cancer cells to display cancer stem-like phenotypes." (PMID 32487125, 2020). "Collectively, these results suggest that the presence of macrophages in tumor tissues potentiates the activity of NFKB resulting in subsequent resistance to anti-TNF therapies." (PMID 32883235, 2020). "When DC1s are stimulated with tumor TNF-α acquire the capacity to induce the differentiation of naïve CD4+CD45RA+ T-cell to Th1 cells." (PMID 32731512, 2020). "Both, the pro- inflammatory cytokines TNF-α, IL-6 and IFNγ and anti-inflammatory cytokines IL-10 and IL-4 were enhanced in the serum compared to tumor bearing control, indicating a cytokine modulatory effect." (PMID 33415123, 2020). "Such cytokines IL-8, IL-6, IL-1β, TNF-α, IL-10, and others can be up-regulated and consequently contribute to tumor progression." (PMID 32277014, 2020). "The interaction of leptin with cytokines can also influence breast cancer progression: leptin acts on both tumour cells and tumour stroma to secrete inflammatory cytokines such as IL-1, IL-6, TNF-α, and growth factors." (PMID 32033341, 2020). "The tumor cells showed significant hemorrhagic necrosis due to a disruption in the neoangiogenic vasculature induced by TNFα." (PMID 32774773, 2020). "The ASO approach was used to induce downregulation of TNFR1, allowing tumor therapy with high dose TNF, i.e., protecting animals from systemic TNF-induced toxicity." (PMID 32528961, 2020). "We performed ELISA assay to determine the expression of IL6 and TNF-α in the blood of tumor-bearing mice." (PMID 32742480, 2020). "The pathways engaged in the synthesis of IL-6, IL-1, IL-12p70, and TNF-α in DCs were affected by HHP-treated tumor cells." (PMID 32340275, 2020). "miR-240-5p regulates the expression of key genes involved in the immune pathways, including the expression of cytokines such as tumor necrosis factor (TNF), contributing in the remodeling and reprogramming of the tumor microenvironment." (PMID 32316552, 2020). "In Walker-256 tumor-bearing rats increased systemic inflammation was observed with animals presenting elevated plasma TNF-α and IL-6 compared to non-tumor-bearing control animals." (PMID 33329046, 2020). "Taken together, our results support that tumor encounter modifies the TNF/RIPK3-dependent induction of caspase-8 activity to TNF/RIPK3-dependent caspase-1 activity after PH." (PMID 33178579, 2020). "It is postulated to restrict tumor angiogenesis through TNF-induced, TNFR1-FAS-mediated endothelial cell apoptosis." (PMID 33339178, 2020).
tumor (continued). "Altogether, these data predict that defects in the cGAS/STING cytotoxic pathway (or TNF/IFN pathways ) should shape tumor evolution during anti-mitotic therapy." (PMID 31937780, 2020). "While the delivery of SM as a single therapy had minimal efficacy in comparison to untreated controls, the combination of TNF/Mel with SM (red line), delivered by ILP, significantly delayed tumour growth when compared to TNF/Mel alone." (PMID 32419365, 2020). "In vivo studies were also performed, showing larger amounts of ATP secretion and calreticulin translocation in tumor tissue from the treatment group as well as higher concentrations of TNF-α and IFN-γ in serum taken from treated mice." (PMID 33260534, 2020). "Along this process, tumor cells reduce their immunogenicity, and among other features, they become resistant to the cytotoxic activity of TNFα." (PMID 32391269, 2020). "Nevertheless, their expression levels cannot indicate SMs sensitivity, as SMs can induce tumor cells death through both TNFα-dependent and TNFα-independent pathways." (PMID 32325691, 2020). "It was postulated that TNFα upregulates expression of IFNγ receptors trough the NF-κB pathway resulting in enhanced IFNγ signaling in HCC cells thereby promoting tumor growth." (PMID 32486375, 2020). "Based on previous studies in hepatocytes and a tumor cell line, proinflammatory cytokines IL-6 and TNF-α are involved in regulation of CYP1B1 expression." (PMID 32260461, 2020). "Pro-inflammatory cytokines like IL-6, TNFα and IL-17, increase the proliferation rate of other inflammatory immune cells and prime the tumor to overcome suboptimal microenvironmental conditions including lack of nutrients, growth factors and hypoxia." (PMID 33343570, 2020). "Two different strategies have been developed to reduce systemic toxicity of TNF or IFNγ while preserving their anti‐tumor activity." (PMID 31916677, 2020). "We showed that Etanercept reduces the transcript levels of TNF-α, IL10 and CCL22, all of which are associated with tumor progression." (PMID 32883235, 2020). "Cytokines such as Interleukin 6 (IL-6), Tumor Necrosis Factor alpha (TNF-α), Interleukin- 1β (IL-1β) and Interleukin 10 (IL-10), which are released peripherally and in the tumor microenvironment, can act locally in reciprocal signaling interactions." (PMID 33126617, 2020). "The combination of SMs and oncolytic virus therapy, both of which have significant immunomodulatory properties, can synergise to promote anti-tumour T cell responses due to apoptosis of SM-treated cells triggered by TNF secreted during viral infection." (PMID 31947615, 2020). "This study was instrumental in elucidating the role of macrophage-secreted TNF-α in endothelial monolayer permeability and tumor intravasation potential." (PMID 32002106, 2020). "Rats receiving a single dose of human TNF-α resulted in increased muscle proteolysis and anorexia, while tumor bearing rats receiving TNF-α inhibitors had markedly improved nutritional intake and body weights." (PMID 33329046, 2020). "Several factors, such as interleukins (e.g., IL-1, IL-6, IL-8), tumor necrosis factor type α (TNF-α), and others are produced by tumor cells and activated by immune cells in tumor milieu." (PMID 32121320, 2020). "Another biologic rationale is the presence of tumor necrosis factor-alpha and interleukin-6 induced signaling, which can promote tumor growth." (PMID 33243216, 2020). "First, TAMs highly express Arg1, VEGF, osteopontin, MMPs, IL-10, TGFβ, and TNFα and thus inhibit the anti-tumor immune response." (PMID 32518979, 2020). "TNF-α pathway-mediated inflammatory responses play decisive roles in tumour development, including initiation, promotion, invasion, and metastasis." (PMID 32333046, 2020). "Interferon gamma (IFN-γ) and tumor necrosis factor (TNF-α) secreted by activated T-cells can also induce PD-L1 expression on tumor cells and antigen-presenting cells (APCs)." (PMID 32733486, 2020).
tumor (continued). "Chemotherapy drugs, the tumor itself, and the patient's long-term physiological and psychological stress can lead to increased production of inflammatory cytokines such as tumor necrosis factor alpha (TNF-α), interleukin 1 (IL-1), and interleukin 6 (IL-6)." (PMID 32684930, 2020). "Polychromatic immunofluorescence verified the finding that anti-tumor (TNFα) and pro-tumor (IDO) markers were co-expressed in certain GAM subgroups." (PMID 32457755, 2020). "At the same time, mice injected with these cells showed reduced inflammatory edemas, decreased leukocyte infiltration and augmented levels of soluble receptor 1 of TNF-α (sTNF-α R1), whereas TNF-α itself was downregulated in tumor tissues." (PMID 33287312, 2020). "The beneficial effect of TNF-α expression on concomitant Doxil® therapy was proven in all tested tumor models including metastases." (PMID 32917034, 2020). "In this study, we now demonstrate the efficacy of tumor vasculature‐targeted TNF and IFN‐γ AcTakines (resp." (PMID 31912630, 2020). "The CD68, IL-6, and TNF-α expression in tumor cells was significantly higher in FOBT-positive patients than in FOBT-negative patients (all p<0.05)." (PMID 33643891, 2020). "Similar tumor inhibition and mortality were found in a subsequent publication which also correlated high plasma levels of IFNγ and TNFα with toxicity." (PMID 33178203, 2020). "The TNFα-induced increase of tumor cell motility and CXCL8 production by contact TNBC co-cultures with MSCs were inhibited by GSI, and direct involvement of Notch1 was demonstrated in up-regulating CXCL8 production." (PMID 32605277, 2020). "Activated CTLs secrete several cytokines such as interferon-gamma (IFN-γ), tumor necrosis factor-alpha (TNF-α) and the crucial cytolytic mediators (perforin, granzyme, etc.), which improve antigen presentation and mediate anti-tumor effects." (PMID 33333816, 2020). "Altogether, increased TNFα in the microenvironment and the induction of caspases in tumor cells favors the induction of apoptotic and necroptotic cell death." (PMID 33036368, 2020). "The sustained responders to Y90-RE had increased expression of inflammatory activating markers and TNF-α on tumor infiltrating T cells and peripheral blood mononuclear cells (PBMCs) after treatment." (PMID 31952209, 2020). "Mast cells produce angiogenetic mediators, such as VEGF, bFGF, heparin, histamine, SCF, IL-8, NGF, TNF-α, tryptase, in forming tumor vessels and the followed invasion or metastasis of cancers." (PMID 32023940, 2020). "The addition of anti-TNFα neutralizing antibodies infliximab or etanercept reduced tumor desmoplasia and cooperated with chemotherapy in delaying tumor growth and mouse survival." (PMID 32961746, 2020). "TNFα is crucial not only to mediate killing of several tumor types, but also for proper proliferation of T lymphocytes, B cells, NK cells, macrophages, and dendritic cells (DC)." (PMID 32391269, 2020). "As a result, there is an increased infiltration of cells of the immune system in affected tissues, especially in adipose tissue and skeletal muscle, and consequent release of tumor secreted products, mainly TNFα and IL-6, among others." (PMID 33613297, 2020). "C-reactive protein (CRP) is increased in PCa patients due to the systemic inflammatory response to the tumor, and tumor necrosis factor-α (TNF-α) is an upregulating factor of CRP." (PMID 32784500, 2020). "Flow cytometry analysis of tumor-infiltrating CD8s revealed that YAP-deficient cells produce more IFNγ and TNFα." (PMID 32322254, 2020). "The cytokines TNF-α and IL-6 can induce tumor cell apoptosis and result in tumor necrosis, acting as critical roles in mediating the signal transduction which stimulates the immune defense system." (PMID 33126624, 2020). "As an example, TNFα, which is a recognized anti-tumor cytokine and a component of cGAS-mediated anti-tumor response, is also a central driver of RA pathogenesis." (PMID 32774773, 2020).
tumor (continued). "TNFα has pluripotent effects on tumorigenesis and cancer progression and an autocrine function in the tumor microenvironment." (PMID 32602581, 2020). "In mice, inducible IL-12 secretion by CAR-T cells resulted in the recruitment of activated TNF-α-producing macrophages which directly contributed to tumor elimination in a TNF-α-dependent manner." (PMID 32625204, 2020). "In EOC ascites, M1 are able to produce IL-12 and TNF-α, which will prompt a cytotoxic T-cell response against tumor cells." (PMID 32630708, 2020). "TNF-dependent anti-tumour activity mediated by bacillus Calmette-Guérin (BCG)-stimulated neutrophils following SM treatment has been reported." (PMID 31947615, 2020). "Depleting FAP-expressing cells provides some tumor growth control through a process involving IFNγ and TNFα." (PMID 33050580, 2020). "Macrophages of mice with intestinal dysbacteriosis release pro-tumorigenic cytokines (e.g., IL-6 and TNF) and stimulate in vivo the growth of tumor xenografts, while promoting colon cancer cell proliferation and EMT in vitro." (PMID 32962159, 2020). "Compared with those treated with bevacizumab alone, tumors treated with both bevacizumab and anti-TNFα nanobody exhibited significant tumor growth suppression." (PMID 33214550, 2020). "These cells directly or indirectly kill tumor cells by secreting IFN-γ, macrophage activating factors (MAF) and TNF-α or simply by activating apoptotic cascades in tumor cells." (PMID 32942580, 2020). "It was shown that treatment of the endothelium with TNF or coculture with macrophages resulted in rapid and increased numbers of tumor cell–endothelial cell attachment events." (PMID 33330508, 2020). "In vitro studies have shown that TNF-α directly kills various human tumor cells, such as melanoma, breast cancer, and cervical cancer cells." (PMID 32149121, 2020). "Cytokines and growth factors including IL‐8, TNF‐α, G‐CSF, and GM‐CSF are known to prolong neutrophil survival and are also known as positive driver of tumor growth, angiogenesis, and metastasis." (PMID 31925882, 2020). "In this study, we have identified the tumor endothelium as the target cell for the antitumor effect of TNF and IFN‐γ." (PMID 31912630, 2020). "In the Hepa 1–6 tumor model, injection of entolimod 1 h prior to TNF/D-GalN combination treatment also achieved mouse survival (protected against TNF/D-GalN toxicity), but affected tumor growth somewhat differently." (PMID 32027657, 2020). "Of note, D1143 augments the tumor-specific adaptive immunity induced by ablative radiation therapy, while reducing host immunosuppressive cell infiltrates in the tumor microenvironment in a TNFα, IFNγ and CD8+ T-cell-dependent manner." (PMID 31978106, 2020). "In contrast, mast cells can exhibit antitumour activity directly through tumour cell cytotoxicity mediated by TNF‐α and ROS or indirectly through the release of interleukin‐9 and heparin and the stimulation of dendritic cell maturation." (PMID 32175651, 2020). "Bregs suppress the immune responses against HCC primarily via the CD40/CD40L mediated production of IL-10 and TGF-β, which down-regulate TNF-α that is critical for halting tumor progression." (PMID 33230233, 2020). "Tumor cells that highly express TNF-α stimulate M1-type macrophage infiltration and secrete IL-6, which damages mucosal epithelial cells and further causes recessive hemorrhage." (PMID 33643891, 2020). "The expression of PD-L1, interferon-gamma, and tumor necrosis factor-alpha protein was increased significantly in anti-PD-1-treated tumor-bearing mice." (PMID 32244307, 2020). "They stimulate regulatory T cell differentiation and secrete several factors (e.g., TGFβ, TNFα and IL-10) to create a favorable environment for tumor progression and to inhibit the anti-tumor effects of immune cells." (PMID 32344813, 2020).
tumor (continued). "In the occurrence of cancer, EIF4A3 regulates cell cycle and apoptosis via the TNF-α/NF-ĸB signaling pathway and other important signaling pathways, promotes tumor cell migration and invasion, and the formation of drug resistance." (PMID 33149201, 2020). "The further induction of cytokines such as IFN-γ in T cells was evident, which, together with TNF-α, induce cancer/tumour killing." (PMID 32466253, 2020). "It has been stated that TNFα can induce apoptosis and promote tumor growth in TNBC, depending on the specific cell line and the cellular context in which it is found." (PMID 32391269, 2020). "In MDA-MB-231-resistant tumor-bearing mice, the content of TNFα in serum kept going up consistent with CCL1, a chemokine of M2b macrophage." (PMID 33214550, 2020). "Pro-inflammatory cytokines such as IFN-γ and TNF-α can help stimulate effector cells and enhance tumor cell recognition of cytotoxic effector cells." (PMID 32547541, 2020). "Acute inflammatory cytokines are previously reckoned as M1-like activators, such as IL-1β, TNF-α, and IFNγ, which are exemplified classically in multiple tumor models." (PMID 33505964, 2020). "In CRC, IL-6 and TNFα participate in most steps of cancer progression, including tumor initiation, proliferation, migration, and angiogenesis." (PMID 32317968, 2020). "Macrophages are phagocytic cells that play a major role in the host defense system by phagocytosis or by the production of NO and TNF-α to kill foreign infectious bacteria, agents and even tumor cells." (PMID 32560675, 2020). "Potentially promoting an inflammatory environment in the tumour, we report the release of inflammatory cytokines TNF and IFN-γ from the T cell population." (PMID 33302918, 2020). "In supernatants from tumour cell killing assays, we found a similar immune mediator profile (TNFα, MCP-1, IL-10, CXCL-10, IL-1β, IL-6, and IL-23) to that previously detected with IgE cross-linking on the surface of monocytes." (PMID 33203088, 2020). "The most common inflammatory molecules released in the microenvironment by tumor-associated macrophages (TAMs) are the EMT-inducers TGF-β1 and TNFα." (PMID 32257947, 2020). "TNFα—predominantly produced by bone marrow-derived cells—mediates downstream anti-tumor immunity and tumor cell necrosis." (PMID 32774773, 2020). "In cancer cells, elevated production and secretion of TNF-α acts in a paracrine and autocrine manner to promote tumor proliferation, progression and ultimately metastasis." (PMID 32317702, 2020). "Our findings indicated that following TNFα stimulation of tumor-stroma co-cultures, NF-κB activation has led to CXCL8 induction, partly through a Notch1-dependent process." (PMID 32582148, 2020). "The main subpopulation of CD8+ T cells, namely the CTLs producing IFN-γ, TNF, and cytotoxic molecules including perforin and granzymes, are the best effectors in tumor rejection because of their specificity and cytotoxic activity against tumor cells." (PMID 33022971, 2020). "In contrast, lymphocytes can secrete some cytokines (IFN-gamma and TNF-alpha) involved in tumor growth control and in systemic defenses." (PMID 32325965, 2020). "On the other hand, the role of TNF-α in chronic inflammation and its tumor-promoting effect have also been proven." (PMID 32149121, 2020). "One of the most influential cytokines in tumor microenvironment is Tumor Necrosis Factor-alpha (TNF-α), long known for its dual effects cancer." (PMID 32883235, 2020). "CD163 is a macrophage- and bone marrow-derived monocyte-specific transmembrane protein whose expression is induced by tumor promoting cytokines, such as IL-6 and IL-10, and reduced by inflammatory stimuli, including TNF-α and IFN-γ." (PMID 33212945, 2020). "Methods to detect multiple cytokines, such as TNFα, should be considered when assessing the presence of tumor-specific TILs and their response in cancer patients." (PMID 32194559, 2020).